TP73 (tumor protein p73)
Diseases named in the same sentence as TP73 in open-access papers (continued):
Sharing a sentence is not in itself a finding about the gene and the disease.
cancer (continued). "Interestingly, we also show that seven major gene regulators (TP73, RICTOR, NUPR1, NKX2‐3, MYCN, IL10, and EPO) involved in inflammation, oxidative stress, DNA damage, and cancer processes were affected by MP radiation." (PMID 29786969, 2018).
infection (4 papers, 2014 to 2025). The state of being infected such as from the introduction of a foreign agent such as serum, vaccine, antigenic substance or organism. "We found cytokines like IFNγ, IL-4, IL-13, IFNβ1, TNFα, and transcriptional regulators such as HIF1α, STAT1, CTCF, TP73, IRF1, MXD1, ATF4, SPI1 mediate macrophage activation upon infection." (PMID 35789215, 2022). "Mock infection and treatments of cells with non-oncolytic Ad-derived vectors either without a transgene (Ad.Empty), or vectors able to transduce the cells either with an shRNA against GFP (Ad.shGFP), an shRNA against HDAC1 (Ad.shHDAC1) or TP73 (Ad.p73) were used as expression controls." (PMID 25071017, 2014).
hematological malignancies (3 papers, 2011 to 2022). "Similarly, downregulation of TP73 was associated with a worse OS in hematological malignancies of myeloid origin." (PMID 35756491, 2022). "Additionally, aberrant TP73 expression has been linked to hematological malignancies and their poor prognosis." (PMID 35756491, 2022). "In hematological malignancies, TP73 that does not display frequent mutations is known to be silenced by CpG methylation." (PMID 29295500, 2017).
CNS tumors (1 paper, 2024). "The most commonly overexpressed genes in CNS tumors included TOP2A (67%), BIRC5 (59%), CDK4 (50%), BRIP1 (49%), NOTCH1 (41%), SMO (39%), and TP73 (39%)." (PMID 38347552, 2024).
genetic disorder (1 paper, 2021). "Lastly, P73 contributes to neural and immune system functions but no genetic disorder has been linked to the gene, possibly because any such TP73 mutation might produce severe defects that are embryonically lethal." (PMID 33672023, 2021).
TP73 also shares sentences with these, for which no sentence is quoted: leukaemia (3 papers); lung adenocarcinoma (3); adenocarcinoma (2); breast invasive carcinoma (2); pancreatic adenocarcinoma (2); prostate adenocarcinoma (2); rectum adenocarcinoma (2); acute myeloblastic leukaemia (1); anal carcinoma (1); anaplastic glioma (1); bacterial infection (1); Barrett esophagus (1); bladder tumors (1); brain disorder (1); brain injury (1); cardiovascular diseases (1); cervical squamous cell carcinoma (1); cholangiocellular carcinoma (1); chordoma (1); cognitive diseases (1); colon adenocarcinoma (1); colon cancer (1); deafness (1); diffuse large B-cell lymphoma (1); endocervical adenocarcinoma (1); esophageal squamous cell carcinoma (1); extrahepatic bile duct carcinoma (1); Fanconi anemia complementation group A (1); Follicular Thyroid Carcinoma (1); HCMV infection (1).
A further 31 diseases each share a sentence with TP73 in 1 paper.